BRAF (B-Raf proto-oncogene, serine/threonine kinase)
Diseases named in the same sentence as BRAF in open-access papers (continued):
Sharing a sentence is not in itself a finding about the gene and the disease.
tumor (continued). "Furthermore, as the biomarker LDH correlates with the tumor burden in melanoma patients, it might be necessary quantifying tumor burden independently by quantitative liquid biopsy based on the BRAF mutation." (PMID 36006943, 2022). "Furthermore, exact primary tumor location is associated with a rather continuous increase in anti-EGFR antibody efficacy from proximal to distal segments of the colorectum in patients with RAS/BRAF wild-type tumors." (PMID 35158793, 2022). "Moreover, we analyzed the correlations between EMT signature with relevant clinical characters, and found significant differences in terms divided by age, gender, BRAF mutation, residual tumor, focality, extrathyroidal invasion, histological type, and TNM stage." (PMID 35608185, 2022). "Therefore, we concluded that a combination of tumor size and BRAF mutation could clearly differentiate AUS/FLUS into three categories with varying risk for more precise management of Bethesda category III (AUS/FLUS) lesions." (PMID 35197932, 2022). "As both conventional AM and UAM have been found to harbor BRAF p.V600E mutations, aggressive and destructive tumors could be candidates for BRAF-targeted therapy that has the potential to reduce tumor size and ultimately enable a conservative surgical procedure." (PMID 36378285, 2022). "Hence, GB harboring a BRAF V600E mutation might exhibit a different, more invasive tumor biology than that of a BRAF wild-type GB." (PMID 35130969, 2022). "Therefore, we tend to consider MA to be an indolent tumor, and cases 31-39 in our study are more suitable to temporarily named atypical MA rather than malignant MA or epithelial-predominant WT resembling MA with the BRAF V600E mutation." (PMID 36313688, 2022). "Mutated BRAF non-V600E tumours are associated with younger age, lower degree of cellular differentiation, less frequency mucinous histology, microsatellite stability, left-sided disease and a less aggressive evolution of cancer than patients with mutated BRAF V600E or wild-type BRAF tumours." (PMID 36819812, 2022). "However, BRAF V600E mutations coexisted in both morphological areas of the tumor." (PMID 36313688, 2022). "Additionally, the tumor now harbored a de novo BRAF H608Y mutation." (PMID 33048186, 2021). "Finally, a different BRAF status of the metastasis with respect to known primitive tumors could also be the expression of another tumor with a different mutational status." (PMID 34207125, 2021). "Thus, FOLFOXIRI plus bevacizumab is currently regarded as a standard first-line option in mCRCs, especially as a neoadjuvant treatment in fit patients with initially unresectable diseases or in patients with good ECOG PS and a poor prognosis tumor (i.e., right colon or BRAF-mutated tumors)." (PMID 34299337, 2021). "Pre-clinical studies have shown that pan-PI3K inhibitors, AKT inhibitors, or mTOR inhibitors, in combination with MEK inhibitors, may deliver promising tumor suppressive effects in KRAS or BRAF-mutant tumors; however, the associated toxicity may still limit clinical benefits." (PMID 33809714, 2021). "Likewise, a non‐V600 BRAF mutation was detected after 3 months of treatment with second‐line ceritinib treatment, suggesting that resistance of the tumor to the ALK‐I could be due to the acquisition of the BRAF mutation." (PMID 34058070, 2021). "Hence, tumor heterogeneity might have caused misclassification of BRAF mutation status, thereby negatively affecting the results." (PMID 33915880, 2021). "The study also shows that, while there is a small rate of error with the commonly used tests based on the tumor tissue sample, retests using blood samples may be a less invasive and rapid alternative for identifying the BRAF mutation status and selecting the right treatment for these patients." (PMID 34298804, 2021).
tumor (continued). "Furthermore, in a novel AlbuMus RAG1 knockout model (AlbuMus RAG1 KO) bearing EGFR-positive BRAF mutated tumours, we demonstrate superior anti-tumour effects after a single dose of the Albu-LiTE construct compared to a conventional Fc-less LiTE format and a full-length anti-EGFR monoclonal antibody." (PMID 33686177, 2021). "However, castPCR assay detected a BRAF(c.1799T>A;p.V600E) mutation in this tumor." (PMID 34326811, 2021). "It is interesting to note that many of these carcinomas are characterized by the presence of well-differentiated areas, and BRAF-V600E is present in both tumor components assuming the hypothesis that this mutation is an early event in tumor development and dedifferentiation." (PMID 33572167, 2021). "Moreover, receiver operating characteristic (ROC) curves for maximum standard uptake value (SUVmax) of the primary tumor were generated along with analysis of the target tissue to nontarget tissue ratio (T/NT) for predicting the efficacy of KRAS/NRAS/BRAF mutations in CRC." (PMID 34239564, 2021). "Furthermore, greater growth inhibition of EGFR-positive BRAF mutated tumours was measured following a single dose of Albu-LiTE-HB construct compared to the Fc-less LiTE format and a full-length anti-EGFR monoclonal antibody in a new AlbuMus RAG1 knockout model introduced in this work." (PMID 33686177, 2021). "The study shows that plasma testing using cfDNA is a less invasive and rapid alternative to confirm the presence of BRAF mutations versus tumor biopsies, and may help in the early identification of patients who are more likely to benefit from treatment with BRAF inhibitors." (PMID 34298804, 2021). "Additionally, we determined whether tumour mutation burden (TMB) or BRAF status were prognostic markers of survival." (PMID 33077847, 2020). "Mutations in BRAF are known to induce senescence in tumor cells in serrated lesions, suggesting that type A1 TSAs may maintain the stable status of tumor cells owing to BRAF mutations and subsequent cellular senescence in TSA cells, promoting the progression of TSA." (PMID 32535664, 2020). "Importantly, Garman and collaborators, after characterizing 30 NF1 mutant tumor biopsies, patient-derived xenografts and cell lines, documented the coexistence of non-V600E BRAF, RAS, and other characteristic MAP kinase-associated genes mutations in 87% of the analyzed cases." (PMID 32825562, 2020). "The CIMP pathway is important in promoting hypermethylation of various tumor suppressor genes, mainly methylated-DNA-protein-cysteine methyltransferase and DNA mismatch repair protein, together with mutations of the V-raf murine sarcoma viral oncogene homolog B1 (BRAF) and MSI26." (PMID 32587771, 2020). "This may capture intratumoral transcriptomic heterogeneity in CRCs with more than one subtype signature coexisting in the same tumor and improve assessment of prognosis and its association with RAS/BRAF wild-type statuses and tumor sidedness in patients with mCRC treated with anti-EGFR therapy." (PMID 33015526, 2020). "The presence of a positive sentinel node leads to a lymph node dissection of the invaded area, and subsequently, to adjuvant treatment with anti-PD1 immunotherapy or with BRAF inhibitors (BRAFi), depending on whether the tumour harbours a BRAF codon 600 mutation." (PMID 32664549, 2020). "Subgroup sample size may have limited the detection of small to moderate risk associations but, taken together, our findings do not support a major role for these biomarkers in the development of specific subtypes of CRC based on KRAS and BRAF mutations or MSI status in the tumor." (PMID 32210264, 2020). "Although the precise molecular mechanism linking Spry1 to EMT needs further investigation, Spry1 expression appears to be critical for tumor induction, maintenance, and progression, and may potentially represent a novel vulnerability of CM harboring BRAF mutations." (PMID 32444628, 2020).
tumor (continued). "The mRNA study, however, was performed on the same region of the tumor that had been selected for proteomics and detected a higher number of samples containing the BRAF V600E mutation; thus, this data provided a more valuable measure against which the mass spectrometry results could be compared." (PMID 31835364, 2019). "The level of ctDNA BRAF mutations correlated with clinical response to treatment, with greater reduction in responding patients compared to those with stable or progressive disease (p = 0.004) and was correlated to percentage tumor change (p = 0.001, R = 0.414)." (PMID 31824558, 2019). "Moreover, BRAF mutations may also promote immunosuppressive effects into the tumour microenvironment (TME) by inducing the production of VEGF and promoting the CD73 expression and subsequent increased levels of adenosine." (PMID 31581559, 2019). "Interestingly, inhibition of oncoproteins such as BRAF may also be associated with increased expression of HLA molecules and heat shock proteins, which can further contribute to a tumor’s visibility." (PMID 29780391, 2018). "Among 80 PTMC specimens, only one tumor harbored the TERTp hotspot mutation C228T, while two other specimens displayed unknown TERTp alterations −77 C->T and −162 C->T, with the latter one also being positive for the BRAF V600E mutation." (PMID 30200646, 2018). "Thus, we explored whether patients with BRAF V600E or USP48-mutated tumor display distinct clinical features." (PMID 30093687, 2018). "A recent study showed a sustained proliferative phenotype of SOX2+ cells in human PCP (known to predominantly harbor BRAF mutations), and advanced the hypothesis that these cells may be driving the growth of the tumor because they represent the major proliferative cell population within the tumor." (PMID 29255445, 2017). "Therefore, it is reasonable to surmise that combining a BRAF inhibitor and cabozantinib may be a useful approach in patients with BRAF mutation-positive tumours and may delay or prevent the development of resistance." (PMID 28103611, 2017). "Because of the rarity of this observation, it is not clear whether the concomitant KRAS and BRAF mutant tumors have a different biology and natural history than singly KRAS or BRAF mutant tumors, or which of the two mutations play the dominant role in driving the tumor proliferation." (PMID 28580315, 2017). "We evaluated the significance of RAS/PIK3CA/BRAF tumor mutations in patients receiving combination chemotherapy with Bmab as the first-line treatment for mCRC, and we assessed whether these mutations could be used to select patients who would derive the greatest clinical benefit from Bmab." (PMID 28068936, 2017). "The incidence of BRAF mutation may vary depending on tumour stage." (PMID 28067827, 2017). "Other individual HCLc tumours that display distinct gene mutations that differ entirely between patients may conceptually harbour specific driver mutations that could also co-operate with mutant BRAF to promote malignant transformation." (PMID 26871591, 2016). "Hence, this small intestinal NET patient with BRAF V600E mutation showed tumor progression after pazopanib treatment, although at the time of clinical trial enrollment, the genomic information was not available to the clinician because this trial was not a genome-selected trial." (PMID 26684240, 2016). "Additionally, the tumor was positively tested for BRAF V600 mutation." (PMID 27110424, 2016). "Furthermore, when taking the percentage of neoplastic cells in individual samples and the allelic frequency of the variants into account, in contrast to most mutations in KRAS, EGFR and BRAF, a large proportion of the newly identified mutations appear to be present in only a subset of tumor cells." (PMID 25637035, 2015). "Thus, targeting inhibition of MAPK-ERK signal pathways in cells that harboring KRAS, NRAS or BRAF mutation could suppress tumor growth." (PMID 26567773, 2015).
tumor (continued). "While it is unclear whether the BRAF or TERT mutations in this patient’s tumor had an impact on his early brain-only recurrence or his eventual prolonged survival, ongoing investigation is needed to understand the implications of MBM somatic mutational profiles." (PMID 26597176, 2015). "Consequently, using collected patient questionnaire data from the database of the Department of Pathology, Cancer Hospital, along with the corresponding KRAS and BRAF mutational status, we evaluated the associations between tumor molecular and epidemiological features." (PMID 26530529, 2015). "KRAS/BRAF mutant allele ratio was consistently 1:1 (1.05, 1.06 and 1.00 by pyrosequencing) in 3 subareas re-isolated from cases P5, further supporting the presence of concomitant mutations in the same tumor cell population instead of different tumor subpopulations." (PMID 26498038, 2015). "The presence of the BRAF mutation was associated with classic papillary histology (P = 0.003), capsular invasion (P = 0.001), soft tissue invasion (P < 0.001), positive margins after surgery (P = 0.004), cervical lymph node involvement (P = 0.002), and tumor location at diagnosis (P = 0.004)." (PMID 25712893, 2015). "The identification, careful characterisation, and follow-up of cohorts of patients with HRAS/BRAF mutation positive tumours could enable the natural history of such tumours (e.g., absence of malignant or recurrent disease) and so facilitate personalised management of patients with these tumours." (PMID 25883647, 2015). "Therefore, tumors with BRAF or KRAS mutations were in correlation with elevated serum level of tumor biomarkers of CRC and the association of tumor biomarkers and molecular status may indicate the poor prognosis of these patients." (PMID 26530529, 2015). "However, the paradoxically tumor-enhancing effects of BRAF inhibitors in the case of sub-clonal BRAF or co-existent BRAF and RAS mutations indicate the need for the accurate molecular characterization of patients in order to obtain the most from targeted therapeutic strategies." (PMID 26090869, 2015). "Our data indicate that BRAF mutation testing of tumor tissue should be carried out in LCH patients refractory to conventional treatment to identify those patients that may benefit from the salvage therapeutic option of BRAF inhibition." (PMID 24938183, 2014). "Similarly, KRAS hotspot mutations were identified in five cases and tumours of these patients may respond to MEK/BRAF inhibitors." (PMID 25233892, 2014). "Of note, low tumor cell content may prevent identification of the BRAF V600E mutation by molecular analysis and result in false-negative results, but this limitation has been shown to be overcome by the use of BRAF V600E monoclonal antibody." (PMID 24252190, 2013). "As BRAF mutation has been previously reported to be associated with a particularly poor survival in cases with microsatellite stable (MSS) tumours, we also examined whether the prognostic value of BRAF mutation differs by MSI status, overall and stratified for sex." (PMID 24020794, 2013). "BRAF mutations could also be searched in these tumours, as our case report points out." (PMID 24386625, 2013). "However, adjunct and multikinase inhibitors (sorafenib or sunitinib) may slow the disease progression especially in patients with BRAF V600E mutation in tumor cell lines." (PMID 23607002, 2013). "In addition, case #26 may represent a good example of a patient that may be candidate to a target therapy with a BRAF inhibitor instead of conventional therapy as the neoplasm shows a dominant BRAF mutation in 83% of alleles." (PMID 24236184, 2013). "In our retrospective study, 26.7% of patients, all with KRAS wild-type tumours, who had previously unresectable liver-only metastases, underwent surgical resection after systemic therapy, with R0 resection achieved in 38 patients (21.6%); one of those was patient with the BRAF V600E mutation." (PMID 22933967, 2011).
tumor (continued). "Furthermore, heterogeneity of BRAF mutational status in tumour compared to metastasis may complicate results." (PMID 21439039, 2011). "In addition, this unfavourable effect of TOPK expression on outcome was maintained in multivariate analysis, suggesting that TOPK could represent an important prognostic factor in patients with KRAS-mutated or BRAF-mutated tumours." (PMID 19935791, 2010). "Indeed, the incidence of cyclin D1 overexpression was significantly higher in BRAF-mutated (58%) than BRAF wt tumours (14% P=0.001), and patients with BRAF mutations and cyclin D1 overexpression had significantly decreased PFS (P=0.03) and OS (P=0.01) compared with patients with BRAF wt tumours." (PMID 20485284, 2010). "This may reflect a more indolent course of tumours with KRAS/BRAF mutations." (PMID 19018267, 2008). "Thus, a combination of markers of aggressive behaviour, perhaps including BRAF mutation status, may be useful in improving predictions of tumour behaviour." (PMID 17179987, 2007). "Finally targeting MEK may represent a more potent alternative for tumours with BRAF-activating mutations." (PMID 17179987, 2007). "This study aimed to evaluate the association between primary tumor sidedness, KRAS/NRAS/BRAF mutational status, and VTE occurrence in patients with mCRC treated in the outpatient setting." (PMID 41751211, 2026). "Clinical trials have demonstrated that dabrafenib is effective in pediatric patients with BRAF-mutant LGGs, leading to tumor regression and improved progression-free survival." (PMID 41514664, 2026). "KRAS, NRAS, BRAF, and PIK3CA mutations occur at different frequencies in CRC and exert distinct effects on tumor biology, including the composition and functional properties of the TME, particularly its immune component." (PMID 41596586, 2026). "The ability of BRAFi therapy to overcome those barriers, even if transiently, raised the possibility that co‐administering BRAF/MEKi with ICB would lead to synergistic anti‐tumor immunity." (PMID 41514118, 2026). "We performed a comprehensive, cross-cohort analysis of BRAF, KRAS, and EGFR mutation subtypes using 64,807 cBioPortal tumor samples, 1570 cancer cell lines, and 2714 Belgian clinical cases." (PMID 42253180, 2026). "The RET and ALK alterations were identified in a midpole nodule, whereas BRAF positivity was seen in a separate lower pole tumor." (PMID 42039113, 2026). "Tumor cells, particularly those with KRAS or BRAF mutations, rely heavily on glycolysis for energy production, leading to overexpression of GLUT1 and SVCT2." (PMID 41403402, 2026). "In this analysis of a phase I study (ISRCTN13713551), we evaluated circulating tumor DNA (ctDNA) as a prognostic and predictive biomarker for mosperafenib monotherapy in BRAF V600-mutant mCRC." (PMID 42127914, 2026). "Genetic alterations including BRAF V600E and TERT promoter mutations are associated with dedifferentiated tumor phenotypes and poor radioiodine response." (PMID 42042023, 2026). "Prognostic biomarkers-such as RAS, BRAF, HER2 alterations, mismatch repair deficiency, tumor mutational burden, methylation signatures, and non-coding RNAs-provide insight into tumor behavior and recurrence risk." (PMID 41828475, 2026). "In the tested BRAF KIAA1549 fusion+ tumor, Western blot demonstrated maintenance of expected paradoxical MAPK upregulation in response to dabrafenib treatment." (PMID 41785221, 2026). "Ulixertinib is an oral, ATP-competitive ERK inhibitor that has demonstrated preclinical efficacy in various tumor models, including those resistant to BRAF and MEK inhibitors." (PMID 41514664, 2026). "The clearest signals arise from interaction-based contexts, particularly when sex is interpreted together with tumor sidedness and dMMR/MSI-H or BRAF-linked disease states." (PMID 42073632, 2026).